ASH1L (ASH1 like histone lysine methyltransferase)
Diseases named in the same sentence as ASH1L in open-access papers (continued):
Sharing a sentence is not in itself a finding about the gene and the disease.
breast carcinoma (6 papers, 2015 to 2022). "Overexpression of ASH1L is recurrent in breast cancer and cancer-associated ASH1L mutations have been identified in melanoma, breast, prostate, colon, liver and oesophageal cancer." (PMID 31930303, 2020). "In breast cancer, ASH1L is often amplified at high levels, and high mRNA levels are linked to a lower life expectancy." (PMID 35058979, 2022). "In this study, we identified four PHFs, PYGO2, KDM5B, PHF20L1, and ASH1L, which were most commonly amplified/overexpressed in breast cancer." (PMID 28055972, 2017). "Next, we performed quantitative RT-PCR (qRT-PCR) analysis to measure the mRNA expression level of eight HMTs (SETDB1, ASH1L, SMYD2, SMYD3, SETD1A, WHSC1L1, SUV420H1, and SETDB2) in 20 breast cancer cell lines." (PMID 25537518, 2015). "Among the five most frequently amplified HMT genes (frequency>10%) in breast cancers, four were localized on the long arm of chromosome 1, with SETDB1 at 1q21.3, ASH1L at 1q22, SMYD2 at 1q32.3, and SMYD3 at 1q44." (PMID 25537518, 2015). "For ASH1L, 11 of 20 cell lines; for SMYD2, 14 of 20; and for SMYD3, 6 of 20 breast cancer cell lines had two-fold higher mRNA levels." (PMID 25537518, 2015). "Notably, we found that eight HMTs exhibited high-level amplification in more than 5% of breast cancers, and five of these eight HMTs (SMYD3, SETDB1, ASH1L, WHSC1L1, and SMYD2) had high-level amplification in more than 10% of samples." (PMID 25537518, 2015). "In TCGA breast cancer samples, only reduced expression of GCC2 and ASH1L could show poor RFS." (PMID 33363011, 2020). "In contrast, MCF7 showed higher expression of SETDB1, but not ASH1L and SMYD2, which is consistent with amplification of SETDB1, but not ASH1L and SMYD2, in this breast cancer cell line." (PMID 25537518, 2015).
epilepsy (6 papers, 2021 to 2024). A brain disorder characterized by episodes of abnormally increased neuronal discharge resulting in transient episodes of sensory or motor neurological dysfunction, or psychic dysfunction. "Previous studies have shown that ASD patients with ASH1L mutations have a high occurrence of epilepsy." (PMID 35449559, 2022). "EEG recordings from PFC of mice with Ash1L deficiency showed epileptiform activity (an interictal marker of epilepsy) at 1–2 days before overt seizures, and high amplitude spike- and wave-complexes while displaying seizures." (PMID 34782621, 2021). "To examine whether the mice with Ash1l loss in the brain were more likely to develop epilepsy, we challenged both wild-type and mutant mice by intraperitoneal injection of PTZ, a GABAA receptor antagonist, at a sub-convulsant dose (40 mg/kg) to induce seizures." (PMID 35449559, 2022). "Others and our studies in preclinic mouse models confirmed the causal role of ASH1L in ASD and epilepsy." (PMID 39766886, 2024). "Our transcriptomic analyses have identified a significant effect of Ash1L deficiency in PFC on risk genes associated with ASD, epilepsy, and ID." (PMID 34782621, 2021). "Large-scale human genetic studies have identified ASH1L as a convergent high-risk gene for ASD, epilepsy, and Tourette syndrome." (PMID 34782621, 2021). "Similarly, BGR 3 has phenotypes frequently reported in patients with ASH1L variants including borderline cognitive functioning, ASD, mild bilateral sensorineural hearing loss, and epilepsy." (PMID 38674358, 2024).
cognitive deficits (4 papers, 2021 to 2025). "Moreover, previous research has established a phenotypic range in ASH1L-associated conditions with pathogenic variants linked to severe and mild cognitive impairments, language deficits, and neurobehavioral disturbances." (PMID 39902220, 2025). "We also found significant DNA methylation changes in genes outside of canonical pathways implicated in high-altitude acclimatization (i.e., HIF and RAS), including significant DNA methylation changes in genes associated with cognitive impairment [ASH1L and TNIK]." (PMID 34262470, 2021). "ASH1L mutations result in altered methyltransferase enzyme activity and changes in neuronal morphology, leading to cognitive impairments and disruption of ASH1L’s regulatory functions." (PMID 39902220, 2025). "Our recent studies demonstrate that loss of Ash1l in the mouse brain is sufficient to induce ASD/ID-like behavioral and cognitive deficits, suggesting that disruptive ASH1L mutations are likely to have a positive correlation with ASD/ID genesis." (PMID 35449559, 2022). "Future challenges include understanding the complexity of ASH1L interactions and its non-histone substrates and determining the extent to which cognitive deficits result from the loss of ASH1L activity, either in the formation of circuits or in maintaining their homeostasis and function." (PMID 40469903, 2025). "Interestingly, mutations in genes encoding for the factors that write or read H3K36 methylation, such as NSD1, ASH1L, SETD2, and NSD2, have been linked to NDD with autistic features or cognitive deficits, further stressing the importance of H3K36 metabolism in neurodevelopment." (PMID 40469903, 2025).
facioscapulohumeral muscular dystrophy (4 papers, 2017 to 2024). An autosomal dominant disorder affecting the skeletal muscles of the face, scapula, and upper arm. "ASH1L has been implicated in facioscapulohumeral muscular dystrophy." (PMID 28719625, 2017). "In facioscapulohumeral muscular dystrophy (FSHD), local chromatine decompaction allows lncRNA-DBE-T transcription and therefore the recruitment of trithorax group protein of histone methyltransferase Ash1L, leading to activation of FSHD candidate genes." (PMID 29189723, 2017).
Anxiety (3 papers, 2021 to 2022). Intense feelings of nervousness, tension, or panic often arise in response to interpersonal stresses. "Compared to wild-type controls, Ash1L-Nes-cKO spent about 50% less time exploring the arena center (t = 2.914, df = 36, p = 0.006), indicating the Ash1L-Nes-cKO mice had increased anxiety-like behaviors." (PMID 34145365, 2021). "CNO or DZ did not affect sociability, repetitive behavior, anxiety, or locomotion in the vehicle control group, suggesting that the phenotypes of Ash1L-deficient mice are unlikely due to the pharmacological treatment." (PMID 34782621, 2021). "In the open-field test, Ash1L-deficient mice spent significant less time in the center, suggesting increased anxiety, while they did not exhibit significant changes on locomotion." (PMID 34782621, 2021).
attention deficit-hyperactivity disorder (3 papers, 2023 to 2025). A disorder characterized by a marked pattern of inattention and/or hyperactivity-impulsivity that is inconsistent with developmental level and clearly interferes with functioning in at least two settings (e.g. at home and at school). "Additional pathogenic variants in ASH1L have been associated with Attention-deficit/hyperactivity disorder (ADHD), Tourette syndrome, and epilepsy." (PMID 36845425, 2023).
colitis (3 papers, 2017 to 2024). Inflammation of the colon. "Ash1l-silenced mice are more susceptible to T cell-mediated colitis due to the impairment of Treg cell polarization." (PMID 28598443, 2017). "A current study has indicated that downregulated lnc-Smad3 exerts a protective effect on colitis by recruiting Ash1l to the Smad3 promoter and regulating Tregs polarization." (PMID 30150986, 2018). "We first investigated the susceptibility of Ash1l-silenced mice to the induction of 2,4,6-trinitrobenzene sulfonic acid (TNBS)-induced colitis." (PMID 28598443, 2017). "Altogether, these data indicate that Ash1l prevents the development of T cell-mediated colitis by upregulating Treg cell polarization and function in vivo." (PMID 28598443, 2017). "Here we show that the H3K4 methyltransferase Ash1l facilitates TGF-β-induced Treg cell polarization in vitro and protects mice from T cell-mediated colitis in vivo." (PMID 28598443, 2017). "While WT iTreg cells efficiently protected mice from colitis, Ash1l-silenced iTreg cells failed to inhibit intestinal inflammation and weight loss." (PMID 28598443, 2017). "Moreover, upon TNBS induction, Ash1l-silenced mice had fewer Foxp3+ Treg cells in the spleen and mLN, indicating that Ash1l could promote Treg cell differentiation in vivo under pathological conditions, which is critical for the prevention of overall inflammatory responses in colitis." (PMID 28598443, 2017).
developmental delay (3 papers, 2020 to 2024). "detected a new frameshift mutation (p.Lys808TyrfsTer40) in ASH1L in a patient with multiple congenital anomalies (MCA), who presented with ADHD, learning disabilities, motor, and developmental delay." (PMID 35307981, 2022).
hepatocellular carcinoma (3 papers, 2023 to 2025). A malignant tumor that arises from hepatocytes. "ASH1L overexpression in activated hepatic stellate and hepatoma cells contributes to the development of fibrosis‐associated hepatocellular carcinoma." (PMID 39377228, 2024). "Also, congruent ASH1L gene amplification and mRNA up-regulation was reported in hepatocellular carcinoma." (PMID 37400764, 2023). "Intriguingly, the expression levels of ASH1L, CCL2, and CSF1 further decreased in hepatoma cells if ASH1L was simultaneously knocked down in the cocultured HSCs, and vice versa (data not shown)." (PMID 39377228, 2024). "ASH1L, an H3K4 methyltransferase, is found at higher levels in activated hepatic stellate cells (HSCs) and hepatoma cells." (PMID 39377228, 2024). "We screened out ASH1L, an H3K4 methyltransferase with higher expression levels in both hepatoma cells and activated HSCs, to avoid generating distinct effects when epigenetically targeting these two cell types." (PMID 39377228, 2024). "Positive staining of ASH1L was observed in both hepatoma cells and nonparenchymal cells, with universal strong staining in tumor cells and differential staining in mesenchymal cells." (PMID 39377228, 2024). "However, we cannot rule out the possibility that HSC‐ and hepatoma‐specific ASH1L might directly or indirectly modulate T cells via other pathways independent of M2‐like TAMs." (PMID 39377228, 2024).
liver cancer (3 papers, 2023 to 2025). An epithelial or non-epithelial malignant neoplasm that arises from the liver. "ASH1L may be a small‐molecule therapeutic or immunotherapeutic target against fibrosis‐associated liver cancer." (PMID 39377228, 2024). "Furthermore, ASH1L gene was identified as a driver gene liver cancer." (PMID 37400764, 2023).
microcephaly (3 papers, 2023 to 2025). A congenital or acquired developmental disorder in which the circumference of the head is smaller than normal for the person's age and sex. "Taken together, these data are suggestive of a mechanism through which deficits in ASH1L could underlie postnatal microcephaly through its regulation of the neurotrophin signaling pathway." (PMID 36845425, 2023). "More and more research has reported that ASH1L mutations are associated with various neurodevelopmental disorders, including ID, ASD, and microcephaly (MCA)." (PMID 39902220, 2025). "Mutations in ASH1L have also been reported in severe forms of ASD, presenting with ID, seizures, speech difficulties, and in a small number of cases microcephaly and macrocephaly." (PMID 36845425, 2023). "In addition to the potential role of ASH1L in the control of brain size postnatally, clinical studies suggest that mutations in either NSD1, NSD2, SETD2, or SETD5 have also been implicated in microcephaly." (PMID 36845425, 2023).
anaplastic thyroid cancer (2 papers, 2022 to 2023). "Additionally, ASH1L is overexpressed in anaplastic thyroid cancer (ATC), contributing to its aggressiveness." (PMID 37400764, 2023).
Duchenne muscular dystrophy (2 papers, 2018 to 2022). Duchenne muscular dystrophy (DMD) is a neuromuscular disease characterized by rapidly progressive muscle weakness and wasting due to degeneration of skeletal, smooth and cardiac muscle. "Here we report that Ash1L expression is positively correlated with MF and reduced in Duchenne muscular dystrophy." (PMID 30487570, 2018). "Here, the authors identify Ash1L, a histone methyltransferase, as modulating myoblast fusion via activation of the myogenesis gene Cdon, and observe decreased Ash1L expression in Duchenne muscular dystrophy." (PMID 30487570, 2018). "Furthermore, Ash1L was found to be downregulated in Duchenne muscular dystrophy." (PMID 35159130, 2022).
gastric cancer (2 papers, 2022 to 2024). A primary or metastatic malignant neoplasm involving the stomach. "A recent paper demonstrated that ASH1L (histone-lysine N-methyltransferase enzyme encoded by the ASH1L gene) and its antisense lncRNA ASH1L-AS1 are highly expressed in gastric cancer, and they are associated with a poor prognosis." (PMID 39063217, 2024).
lung adenocarcinoma (2 papers, 2024 to 2025). A carcinoma that arises from the lung and is characterized by the presence of malignant glandular epithelial cells. "Mutations and amplifications are particularly prevalent in lung cancer, with ASH1L alterations being found in ~15% of lung adenocarcinoma (cBioPortal)." (PMID 40044670, 2025). "In agreement, ASH1L depletion markedly reduced the growth of A549 cancer cells, and lung adenocarcinoma patients with low levels of ASH1L have better survival." (PMID 40044670, 2025). "We examined the ASH1L protein expression level in five lung adenocarcinoma cell lines by western blot." (PMID 40044670, 2025). "At the same time, we analyzed the mutation rates of H3K36 enzymes (including NSD1, NSD2, NSD3, ASH1L, SMYD2, SETDB2, SETD3, and SETMAR) in lung adenocarcinoma, which showed that the amplification mutation frequency of H3K36 enzymes was at a low level." (PMID 39119928, 2024).
lung carcinoma (2 papers, 2021 to 2025). "In lung cancer, ASH1L also stimulates migration of cancer cells through Cdk5/p35 pathway." (PMID 34215297, 2021).
melanoma (2 papers, 2020 to 2025). A malignant, usually aggressive tumor composed of atypical, neoplastic melanocytes. "We observed that breast and melanoma cells with higher metastatic potential also expressed higher levels of ASH1L than their parent cells." (PMID 40394007, 2025).
prostate carcinoma (2 papers, 2022 to 2025). A carcinoma that arises from epithelial cells of the prostate gland. "Using prostate cancer (PCa) as a model system, we characterized the loss-of-function and gain-of-function effects of ASH1L on cancer invasiveness and bone metastases." (PMID 40394007, 2025). "Here, authors report that ASH1L cooperates with HIF-1α to induce a pro-metastatic transcriptome in prostate cancer cells, and promotes conversion of monocytes to lipid-associated tumor-associated macrophages in the bone metastatic niche." (PMID 40394007, 2025). "Here, we report that histone methyltransferase ASH1L is genetically amplified and is required for bone metastasis in men with prostate cancer." (PMID 40394007, 2025). "ASH1L is also an emerging oncogene in acute leukemia, thyroid carcinoma, prostate cancer (PCa), renal cell carcinoma, and hepatoma." (PMID 36033518, 2022). "In addition, we found that the ASH1L protein is overexpressed in castrate-resistant prostate cancer (PCa) PC3 and DU145 cells in comparison to PCa LNCaP cells." (PMID 36033518, 2022).
thyroid cancer (2 papers, 2023 to 2025). "Overexpression, copy number amplification, and mutations of ASH1L are recurrently found in different neoplasia, including breast and thyroid cancer." (PMID 37296904, 2023).
absence seizures (1 paper, 2024). "Ash1l+/GT mice showed epileptiform discharges (an interictal marker of absence seizures) on EEG and accompanied with a brief cessation of movement, which demonstrated that Ash1l haploinsufficiency induced absence-like seizures." (PMID 39766886, 2024).
acute leukemia (1 paper, 2021). A clonal (malignant) hematopoietic disorder with an acute onset, affecting the bone marrow and the peripheral blood. "ASH1L histone methyltransferase plays a crucial role in the pathogenesis of different diseases, including acute leukemia." (PMID 33990599, 2021). "Thus, the importance of ASH1L in acute leukemia and other cancers strongly supports its high relevance as an attractive therapeutic target in oncology." (PMID 33990599, 2021).
acute myelogenous leukemia (1 paper, 2023). "Recently, ASH1L function has been linked to leukemogenesis in mixed-lineage leukemia and acute myelogenous leukemia." (PMID 37400764, 2023).
Alzheimer disease (1 paper, 2022). A progressive, neurodegenerative disease characterized by loss of function and death of nerve cells in several areas of the brain leading to loss of cognitive function such as memory and language. "The mutation or loss of Ash1L may cause autistic-like behaviors; and low expression of Serpinf2 is related to Alzheimer’s disease." (PMID 35237591, 2022).
autoimmune disease (1 paper, 2017). A disorder resulting from loss of function or tissue destruction of an organ or multiple organs, arising from humoral or cellular immune responses of the individual to their own tissue constituents. "Combined, these data indicate a potential connection between Ash1l and T cell-mediated autoimmune disease." (PMID 28598443, 2017). "By revealing the opposite regulatory functions of Ash1l and lnc-Smad3 in Smad3 expression, our data provide insights for the epigenetic control of Treg cell fate to potentially aid in the development of therapeutic intervention for autoimmune diseases." (PMID 28598443, 2017).
Autoimmunity (1 paper, 2017). The occurrence of an immune reaction against the organism's own cells or tissues. "Increased induction of Smad3 by Ash1l subsequently facilitates Foxp3 expression, contributing to the polarization of Treg cells and prevention of autoimmunity." (PMID 28598443, 2017). "Next, we sought to investigate whether Ash1l was involved in regulation of T cell-mediated autoimmunity in vivo." (PMID 28598443, 2017).
beta thalassemia (1 paper, 2022). Beta-thalassemia (BT) is characterized by deficiency (Beta+) or absence (Beta0) of synthesis of the beta globin chains of hemoglobin (Hb). "A point mutation of the histone methyltransferase ASH1L has been associated with a beta thalassemia-like phenotype.." (PMID 35330735, 2022). "ASH1L, a histone methyltransferase with H3K4 and H3K36 methyltransferase activity, also plays an important role in erythropoiesis, and has been implicated as a regulator of beta globin, with a point mutation in ASH1L associated with a beta thalassemia phenotype.." (PMID 35330735, 2022).
bladder cancer (1 paper, 2019). "Through integrative analysis, we identified six HMT genes (PRDM9,ASH1L,SETD3,SETD5,WHSC1L1, and KMT2D) that may play a key role in the development and progression of bladder cancer." (PMID 30984543, 2019).
bone metastasis (1 paper, 2025). Transfer of a neoplasm from its primary site to bones. "Considering that HIF-1α is a crucial partner of ASH1L in metastatic cells and agents targeting HIF-1α are currently under clinical investigation, we also evaluated the effects of HIF-1α inhibitor PX-478 in our preclinical model of bone metastasis." (PMID 40394007, 2025).